IFNG (interferon gamma)
Diseases named in the same sentence as IFNG in open-access papers (continued):
Sharing a sentence is not in itself a finding about the gene and the disease.
infection (continued). "Despite the presence of replicating virus, numbers of IFNγ-secreting cells were close to background in TIV NC99 mice, suggesting that single TIV vaccination interfered with the induction of NP-specific T cell responses after infection." (PMID 32582220, 2020). "Lastly, in either the pre-infection or the post-infection treatment of human synovial fibroblasts, the anti-chlamydial activity of IFNγ was not dose-dependent." (PMID 32050567, 2020). "Whereas in response to intracellular BCG, CD4+ T cells were the main cell subset responding to infection, with a proliferation peak at 7 days, NK cells were involved in response to extracellular BCG, with peak IFNγ production at 24–30 h, and a peak of proliferation at 6 days." (PMID 33120910, 2020). "Unlike ADSCs, there was no increase in PGE2 release by THP-1 macrophages upon infection or treatment with IFNγ or TNFα." (PMID 32546788, 2020). "CD8 T-cells upregulate Ly49 receptors quite early during the response as 5 days after infection Ly49+CD8 T-cells account for approximately 10% of total IFNγ-producing CD8 T-cells (data not shown)." (PMID 33488602, 2020). "Together, these data suggest that while individual cytokine levels are similar between SM+ and SM− individuals, SM infection modifies the relationship between different cytokines produced in response to Mtb peptide stimulation, particularly with regards to the TH1 cytokine IFNγ." (PMID 32117277, 2020). "The frequencies of single-positive Pfn+ and double-positive IFNγ+ Pfn+ were not modified after infection of ccl3+/+ and, mainly, ccl3−/− mice." (PMID 32194558, 2020). "Finally, C. psittaci infection induced robust expressions of type Th2 cytokines interleukin (IL)-4 and IL-10, while interferon gamma (IFN-γ) and tumor necrosis factor-α (TNF-α) displayed a significant decrease compared to H9N2 infection alone at 24 hpi." (PMID 32326284, 2020). "Nonetheless, neither specific antibodies, nor increased secretion of IFNγ, IL-4, and IL-10 cytokines, conferred greater protection against infection." (PMID 32916868, 2020). "IFNγ has been suggested as a therapeutic for recurrent NHTi infections but has not been sufficiently tested." (PMID 33101299, 2020). "Moreover, UV-irradiated HSV-1 led to more IL-18 production at 24 hours post-infection, suggesting more robust inflammasome signaling in response to UV-irradiated HSV-1 in both IFNγ stimulated and unstimulated macrophages." (PMID 32101570, 2020). "Immunization with purified A. marginale outer membranes can induce complete protection against infection by homologous strains, probably due to CD4+ T-lymphocyte-mediated Interferon gamma (IFN-γ) release and secretion of immunoglobulin G (IgG)-2 antibodies against outer membrane protein epitopes." (PMID 33233869, 2020). "The most common infection in patients positive for anti-interferon-gamma autoantibodies (anti-IFN-γ AAbs) is disseminated nontuberculous mycobacterial (dNTM) infection." (PMID 32188404, 2020). "Consistent with the ability of VSV to antagonize host gene expression, we did not observe major increases in miR-147b levels following infection as we did in the IFNγ/staurosporine-treated cells." (PMID 33370271, 2020). "In addition, treatment with IFNγ further reduced the intracellular survival of Mtb in THP-PKR macrophages, resulting in a decrease in luminescence of 89% at day 6 post-infection compared to THP-Ø macrophages." (PMID 33552025, 2020). "Following the track of infection-like state in cells, it is known that Rnf213 is transcriptionally induced in endothelial cells via PKR (double-strand-RNA dependent protein kinase) after exposing the cells to IFNG." (PMID 32342250, 2020). "The interferon-gamma (IFNγ) release assay (IGRA), adapted for use in cats from cattle and humans, is a highly sensitive immunological test for MTBC infections, although it is limited in its ability to diagnose and discriminate between infections with NTM." (PMID 33218094, 2020).
infection (continued). "The paucity of differentially expressed cytokine genes at 2 months post-infection was consistent with our previous observation that there was no significant induction of MAP-specific IFNG-secreting cells in either DPP or CPP at 2 months post-infection." (PMID 32547548, 2020). "IFNγ could profoundly inhibit VZV production in ARPE-19, A549, MRC-5 but had only very limited capacity to inhibit infection in MeWo cells, where IFNβ retained the capacity to significantly reduce viral yield." (PMID 32038653, 2020). "Similar to IWR-1-endo, infection with RHΔASP5 did not abolish intracellular parasite burden differences between naïve and IFNγ-stimulated BMDMs." (PMID 33014886, 2020). "In general, in badger studies, the interferon-gamma (IFN-γ) production and peripheral blood mononuclear cells (PBMC) proliferation, measured by lymphocyte transformation assays (LTA), decrease between 12 and 21 weeks post-infection." (PMID 32526872, 2020). "This study reveals a novel mechanism by which infection with enteropathogenic E. coli (EPEC) leads to pyroptosis in intestinal epithelial cells; this process is dependent on the type III secretion system effector Tir, and enhanced by priming with IFNγ." (PMID 33378358, 2020). "Thus, TLR4, IL27, and TNF were activated across all groups; IFNG was exclusively activated by AMTB-127 and AMTB-205; PTGS2 was activated in AMCTs and AMTBs in response to infection with Mtb UT205, whereas TLR2 was only activated in response to Mtb UT127." (PMID 32373118, 2020). "Our results showed that the hippocampus of TB mice exhibited a highly significant increase in the expression of the pro-inflammatory (TNFα, IFNγ, IL12) and anti-inflammatory cytokines (IL4, TGFβ), as well as the enzymes iNOS and IDO from day one post-infection." (PMID 33322180, 2020). "Both Th1 and Th17 T cells expressed TNFα and IL-2, but then progressed to also express IFNγ at day 7 post infection (which show day 14 post infection in both vaccinated and nonvaccinated mice having received a dose of 103, or even 102 IFUs)." (PMID 31993218, 2020). "It is however important to emphasize the fact that infection-induced IFNγ production does not solely result from the presence of activated CD4+ T helper cells." (PMID 32218784, 2020). "In HvG-HCT and infection with WT virus, sufficient numbers of high-avidity CD8+ T cells are able to recognize even limited antigen presentation and thereby become stimulated to secrete IFNγ that relieves immune evasion." (PMID 32351904, 2020). "Elevated levels of IFNγ and TNF were found in Ifnar1−/− mice on day 14 p.i. compared with WT controls, but the levels subsequently declined over the course of infection, and TNF levels were significantly lower in Ifnar1−/− mice on days 28 and 56 p.i. compared with WT controls." (PMID 32101732, 2020). "Having a look at the CD4+IFNγ+TNFa+IL-2+ triple producers, a drastic increase with age was visible independent of infection history (right)." (PMID 32849561, 2020). "Indeed, in mouse models of infection driven HLH and of MAS, overexpression of IFNγ was demonstrated in target tissues." (PMID 31846457, 2019). "Except for Hsd3b1, infection with S. haematobium did not have an influence on Vitamin D pathway associated (VDR, Cyp27b1) or immunological (IL10, IFNG, Foxp3) genes as well as vitamin D plasma levels." (PMID 31673046, 2019). "We extended our analysis beyond the conventional IFNγ response by measuring TNFα, IL2, and IL17a producing T-cells as well, both in the periphery as well as at the site of the infection at various time points after infection." (PMID 31736945, 2019). "Similarly, treatment of bMDM with IL10 siRNA enhanced expression of IL1B, TNF, IL6, IFNG and NOS2 induced by G18 infection." (PMID 31527895, 2019).
infection (continued). "But in the oral L. monocytogenes infection model, intestinal multifunctional γδ+T cells able to simultaneously produce IFNγ and IL-17A can provide enhanced protection against infection and even compensate for the absence of αβ+T cells." (PMID 31354728, 2019). "This infection pathology was thought to be CD4 T cell dependent because Th17 CD4 T cells expanded in the absence of IFNγ." (PMID 30873151, 2019). "Moreover, in the model of infection driven HLH, by exploiting the ability of an anti-mouse IFNγ monoclonal antibody to capture tissue IFNγ and mobilize it in peripheral blood as an immune complex, a massive increase in detectable circulating IFNγ was observed." (PMID 31846457, 2019). "On day 6 post infection 10–30 IFNγ-producing cells per 106 splenocytes for individual peptides were observed, while no spontaneous IFNγ secretion was detected (no antigen)." (PMID 31443439, 2019). "MΦ activation with SNs derived from stimulated LN cells from either infected or naïve mice promoted parasite proliferation 72 h post-infection, as opposed to LPS and IFNγ activation." (PMID 31032234, 2019). "Although infection can be identified through skin tests or interferon gamma release assays, the non-availability of these tests should not preclude prevention therapy, once active TB has been excluded." (PMID 32211351, 2019). "In contrast, our observations here indicate that NK cell-intrinsic deficiencies for Stat3, Il15ra, or Il10r1 do not impact systemic IFNγ production or Lm bacterial burdens at 24 h post-infection." (PMID 31552035, 2019). "Moreover, in accordance with data about the prevalence of a polyfunctional T-cell profile in natural infection, we observed B. anthracis CD4+ T-cells able to produce both IFNγ and TNFα." (PMID 31213220, 2019). "The expression density of IFNγ by lung and splenic ILC1s was not affected by the infection alone as compared to uninfected controls." (PMID 31440243, 2019). "In Mtb-infected/Fe-supplemented rabbits, expression of IFNG, TNFA, and IL1B was significantly down-regulated, whereas expression of IL6 and SMAD6 was up-regulated, compared to placebo-treated animals, at 4 weeks post-infection." (PMID 31382404, 2019). "Interferon-gamma (IFN-γ), tumor necrosis factor-alpha (TNF-α), and interleukins (e.g., IL-6, IL-10) are cell-signaling cytokines that activate and drive differentiation of immune cells upon infection." (PMID 31394828, 2019). "A recent study argues that lipid droplet formation is not a bacterially driven process during infection with the laboratory derived Mtb Erdman, but instead is dependent on IFNγ, and is not a source of host lipids for the pathogen." (PMID 30840702, 2019). "Additionally, these proteins contain the capsid region of DENV, which is one of the main targets of cytotoxic and IFNγ-secreting CD4+ T cells, generated during a natural infection." (PMID 31507591, 2019). "Through the NanoUPLC-MSE technology, we analyzed the proteomic response of Paracoccidioides brasiliensis during the infection of alveolar macrophages primed or not by interferon gamma (IFN-γ)." (PMID 30804901, 2019). "IL-1β, TNFα, IL-6 and IFNγ were not significantly elevated during relapses compared to pre-infection values, and Monokine Induced by Interferon Gamma (MIG) was the only cytokine significantly increased during relapses." (PMID 31536608, 2019). "As predicted, this resulted in the generation of serum and genital anti-gonococcal antibodies, IFNγ production by CD4+ T cells, the establishment of immune memory that can be recalled by challenge infection 1–6 months later, and faster clearance of the challenge infection." (PMID 31681305, 2019). "Many of these proinflammatory mediators, including IL-6, MCP-1, TNFα, IFNγ, RANTES and IL-1β, were also present at high concentrations on days 4 and 6 of infection in the spleen, a major target tissue for SFTSV replication and pathology, as well as other tissues." (PMID 31546590, 2019).
infection (continued). "Interestingly, even in this analysis, levels of IFNγ, TNFα, IP-10, sCD163 and CRP in Group 4 became comparable to those of Group 5, which initiated ART one week post-infection (p = ns)." (PMID 30161247, 2018). "Induction of the MHC-I gene expression was also evidenced in our experimental model of infection by over-expression of NLRC5, a specific transcriptional activator of the MHC-I expression, induced by IFNγ through STAT1 activation, whose coding genes were observed also over-expressed in this study." (PMID 29391047, 2018). "After infection with ME49 strain of T. gondii, gal3−/− mice exhibits a higher parasite burden, delayed inflammatory response in the CNS, and significantly higher concentrations of IL-12p40 and IFNγ in the sera compared with those of gal3+/+ mice." (PMID 30108583, 2018). "While IFNγ neutralization resulted in a somewhat higher bacterial load by day 3 post-infection, the effect was modest and not statistically significant." (PMID 29438281, 2018). "In one of the first studies itk−/− mice on a BALB/c background failed to generate the usual Th2 response upon infection with Leishmania major, but rather mounted a Th1 dependent IFNγ response, which cleared the infection." (PMID 29867957, 2018). "The elimination of MyD88 in cardiomyocytes determined a lower increase in CCL5, IFNγ and TNFα gene transcription during acute infection by T. cruzi parasites of the Y strain, but it did not significantly modify heart leukocyte infiltration and parasitism." (PMID 30067739, 2018). "Accordingly, our previous qPCR results showed an over-expression of interferon-gamma after infection with E75CV1 but not due to E75 infection, at 1 dpi." (PMID 30208957, 2018). "IDO1 induction in response to IFNγ is not affected in bystander cells permitting tryptophan depletion in the infection microenvironment." (PMID 29855501, 2018). "Despite non-transgenic cells become also enriched with IFNγ+ cells upon infection, a higher percentage of P25 transgenic than non-transgenic CD4+ T cells producing cytokines is detected." (PMID 29499041, 2018). "The role played by ROS-producing macrophages at the chronic stage of infection has not been evaluated, but it is likely that most of them are activated by interferon gamma (IFNγ) and producing trypanocidal nitric oxide (NO) and peroxynitrite." (PMID 29672619, 2018). "In this way, it could be a mechanism exploited by the virus to reduce expression of interferon gamma (IFNγ) and HIV-suppressive chemokines to produce a persistent infection." (PMID 29987244, 2018). "Assessing direct ex vivo IFNγ responses confirmed that PD-1 expressing cells were not compromised for infection- or epitope-induced cytokine production." (PMID 30419010, 2018). "According to epidemiological data, a 7-43% proportion of heavily exposed individuals are able to clear the infection before the onset of adaptive immunity, resulting in negative tuberculin skin tests and interferon-gamma (Ifnγ) release assays." (PMID 29208761, 2018). "Unlike the effect on αHV axonal infection, exposure of axons to IFNβ or IFNγ does not reduce retrograde RABV infection in the connected cell bodies nor does it alter axonal transport dynamics of RABV particles." (PMID 30028873, 2018). "Cells infected with the Dengue virus produce nitric acid and protective pro-inflammatory cytokines such as Interferon-gamma (IFN-γ), Tumour Necrosis factor-alpha (TNF-α), interleukin-6 (IL-6) and IL-10 to attract and activate leucocytes at the site of infection." (PMID 30112159, 2018). "In contrast, differences in IFNγ release in cultured supernatants between asthmatic and non-asthmatic donors can be detected as early as 48 h post infection." (PMID 30174671, 2018).
infection (continued). "Although sequential infection and sequential WIV immunization induced virus-specific IFNγ-producing CD4 T cells, depletion of CD4 T cells in this study did not influence the cross-protection, neither in the sequential infection group nor in the sequential WIV vaccination group." (PMID 30356772, 2018). "VIP (10 nM) alleviated the NO2- generation induced by IFNγ and TNFα with and without infection (p<0.001)." (PMID 30252907, 2018). "After infection with CPP-labeled EBs, A2EN cells were cultured in the absence or presence of IFNγ." (PMID 29855501, 2018). "In contrast, the infection induces a potent immune response in the skin mediated by CD4+ T cells, which have an effector phenotype that preferentially produce interferon gamma (IFN-γ) and mediate a transitory DTH reaction." (PMID 29946313, 2018). "The levels of many inflammatory cytokines, including IFNγ and TNFα, did not change or minimally changed throughout infection." (PMID 30596671, 2018). "However, the groups with a single infection, either SA11 at day 6 or EDIM at day 17, had cells that were capable of responding to the challenge and produced a certain amount of IFNγ." (PMID 29942312, 2018). "Unlike IFNγ-producing γδ T cells responding earlier in infection, this clone produced macrophage-colony stimulating factor (M-CSF) and accessory cytokines that influence the myeloid compartment (i.e., CCL5, CCL3)." (PMID 30405634, 2018). "While characterizing the effect of IFNγ on chlamydial growth in A2EN cells at 38 hpi, it was observed to not substantially impair infection or normal development if it was added at the time of infection." (PMID 29855501, 2018). "As the infectious dose (MOI, multiplicity of infection) increased, P25 T cells produced more IFNγ when co-cultured with MHC-matched, but not MHC-mismatched, Mtb-infected TGPMs." (PMID 29782535, 2018). "Although CD24loCD8+ SP were not affected during infection, the CD24loCD4+ SP thymocyte numbers were reduced more in BL/6 compared to Ifnγ−/− mice." (PMID 28091621, 2017). "While IFNγ clearly is necessary for a successful host response to infection, several studies have shown that it is not sufficient, as increased levels of IFNγ were indicative of disease progression rather than protection in mice and humans." (PMID 29312343, 2017). "Previous studies have demonstrated the production of interferon-gamma (IFN-γ), interleukin 12 (IL-12), nitric oxide (NO) and tumour necrosis factor alpha (TNF-α) in early stages of infection and later interleukin 13 (IL-13), interleukin 4 (IL-4) and interleukin 10 (IL-10)." (PMID 28655350, 2017). "We found that lung αβ T cells do not produce detectable amounts of IFNγ at 24 hours post-infection, and the absence of Ly6Chi monocytes did not alter their ability to make IFNγ." (PMID 28384349, 2017). "Th17 cells can potentially play opposing roles in immunity to infection, with cells producing IL17 and IL10 considered to play a protective regulatory homeostatic role and Th17 cells expressing IFNγ in the absence of IL10 being associated with pathology." (PMID 28931830, 2017). "T-cells specific to fungal catalase and Crf1 that express CD154 and IFNγ were identified in patients recovering from invasive aspergillosis, whereas these cells were absent in patients with progressive infection." (PMID 29371571, 2017). "R. typhi-infected CB17 SCID mice that had either received CD8+ T cells from IFNγ-/- or Perforin-/- mice never showed any signs of disease and all of the mice survived the infection." (PMID 28222146, 2017). "We saw more IFNγ spot forming units (SFU) in splenocytes stimulated with AdV capsids from the M1 infected mice vs. WT infected mice, suggesting an increased display of AdV capsid antigens during M1 infection." (PMID 28192531, 2017).